CEBPB (CCAAT enhancer binding protein beta)
Diseases named in the same sentence as CEBPB in open-access papers (continued):
Sharing a sentence is not in itself a finding about the gene and the disease.
clear cell renal cell carcinoma (1 paper, 2025). "CEBPB is located on chromosome 20, It exhibits good diagnostic performance for clear cell renal cell carcinoma, with an AUC of 0.832 and a CI of 0.780–0.884." (PMID 40949418, 2025). "In conclusion, our bioinformatics analysis indicates that the expression levels of CEBPB are significantly elevated in clear cell renal cell carcinoma (ccRCC), which is consistent with existing studies." (PMID 40949418, 2025). "Building on these findings, we explored the expression levels of CEBPB in clear cell renal cell carcinoma (ccRCC) and its clinical significance." (PMID 40949418, 2025). "Immunohistochemical (IHC) staining of clinical specimens was performed to validate the expression levels of CEBPB in clear cell renal cell carcinoma (ccRCC)." (PMID 40949418, 2025).
diabetic neuropathy (1 paper, 2022). A chronic, pathological complication associated with diabetes mellitus, where nerve damages are incurred due to diabetic microvascular injury involving small blood vessels that supply these nerves, resulting in peripheral and/or autonomic nerve dysfunction. "Our data support the idea that IGF-1–LNP may provide a path to safe and effective gene therapy in neurodegenerative disorders, while the CEBPβ and NFAT1 transcription factors could also represent promising targets manipulating endogenous IGF-1 production for the treatment of diabetic neuropathy." (PMID 35298717, 2022).
gout (1 paper, 2025). A condition characterized by painful swelling of the joints, which is caused by deposition of urate crystals. "The results showed that key transcription factors such as CEBPB, STAT3, RELA, and NFKB1 may be involved in the pathogenesis of gout by directly regulating the transcriptional levels of these genes." (PMID 40606658, 2025).
heroin addiction (1 paper, 2016). "In this analysis, we found that the 4-gene model that contained JUN, CEBPB, ENO2, and PRKCB genes had an accuracy rate of 85.5% in the prediction of heroin addiction in this dataset." (PMID 27495086, 2016).
intracranial aneurysms (1 paper, 2024). "An amazing finding was that CEBPB may be the hub gene for ruptured intracranial aneurysms, which was closely associated with the inflammatory response and immune system process." (PMID 38332649, 2024).
leiomyoma (1 paper, 2021). A well-circumscribed benign smooth muscle neoplasm characterized by the presence of spindle cells with cigar-shaped nuclei, interlacing fascicles, and a whorled pattern. "A total of eight leiomyoma-related DEGs (EGR1, CEBPB, IL6, PECAM1, VWF, TNFRSF1A, CD34 and ACE) were found upregulated in MF versus M only." (PMID 33807176, 2021).
leukopenia (1 paper, 2017). "By integrating the regulatory relationships and functions among the gene sets of defense response, CEBPB, IRF protein family, and the transcription factor SP1, the etiopathogenesis of leukopenia can be explored more comprehensively." (PMID 28729650, 2017).
low grade glioma (1 paper, 2024). A grade I or grade II glioma arising from the central nervous system. "Furthermore, when comparing chromatin accessibility analysis between GBM and low-grade glioma (LGG), it was discovered that the SPP1 promoter region contains two GBM-specific motifs, which are consistent with the binding sites of CEBPB in other cell types." (PMID 38994023, 2024).
lupus (1 paper, 2023). "We used adenoviral vectors to construct LN mice with knockdown CEBPB using MRL/lpr lupus-prone mice and analyzed the physiological and autoimmune indices in mice." (PMID 37828427, 2023).
lupus nephritis (1 paper, 2022). Glomerulonephritis in the context of systemic lupus erythematosus. "In summary, we identified the CEBPB-Pim-1 signal axis could promote the activation of NLRP3 inflammasome and pyroptosis of glomerular podocytes, which may serve as a therapeutic target against lupus nephritis." (PMID 36248187, 2022).
melanocytic nevus (1 paper, 2025). A neoplasm composed of melanocytes that usually appears as a dark spot on the skin. "Immunohistochemical analysis of postoperative tissues from UM patients (tumor group) and melanocytic nevus patients (normal group) revealed a significant increase in the expression of CEBPB in the tumor tissues." (PMID 40550050, 2025).
microcephaly (1 paper, 2015). A congenital or acquired developmental disorder in which the circumference of the head is smaller than normal for the person's age and sex. "Other genes within the combined network are involved in neuronal progenitor cell proliferation, a common mechanism underlying microcephaly (RAC1 and GNB1) and neuronal development (CEBPB, L1CAM, MAPT, PAK2, SPTBN1, and YWHAE)." (PMID 25781962, 2015).
Neonatal sepsis (1 paper, 2018). Systemic inflammatory response to infection in newborn babies. "TSPO, ZAP70, CEBPB targeting MAPK14, has-miR-150 targeting BCL11B might affect the pathogenesis of neonatal sepsis." (PMID 30497506, 2018). "In the TF-DEG regulatory network, MAPK14 was targeted by CEBPB, indicating that CEBPB targeting MAPK14 might function in neonatal sepsis through TNF signaling pathway." (PMID 30497506, 2018). "Besides, TSPO, ZAP70, CEBPB targeting MAPK14, has-miR-150 targeting BCL11B might act in the pathogenesis of neonatal sepsis." (PMID 30497506, 2018).
nevus (1 paper, 2022). Nevus (or naevus, plural nevi or naevi, from nævus, Latin for "birthmark") is the medical term for sharply circumscribed[1] and chronic lesions of the skin or mucosa. "As a result, CEBPB was significantly downregulated in SKCM tumor tissues, which was further confirmed by another independent cohort GSE46517, which included 73 metastatic SKCM samples and seven normal skin samples (primary and nevus samples were excluded from this study)." (PMID 36353635, 2022).
Oral ulcer (1 paper, 2020). Erosion of the mucous mebrane of the mouth with local excavation of the surface, resulting from the sloughing of inflammatory necrotic tissue. "Therefore, abnormal expression of CEBPB might lead to dysregulation of the immune and inflammatory response, and then increase the risk of contracting an oral ulcer." (PMID 32699208, 2020).
pilocytic astrocytoma (1 paper, 2015). Pilocytic astrocytoma is a rare subtype of low-grade glioma of the central nervous system characterized by a well circumscribed, often cystic, brain tumor with a discrete mural nodule and long, hair-like projections that extend from the neoplastic astrocytes. "In pilocytic astrocytomas, we observed up-regulation of IGFBP7 and CEBPB, both of which are major transcriptional inducers of SASP-related genes." (PMID 26682910, 2015).
skin melanoma (1 paper, 2022). "We speculated that CEBPB might affect skin melanoma mainly by influencing other cell types in the tumor microenvironment rather than the malignant cell itself." (PMID 36353635, 2022).
synovial sarcoma (1 paper, 2020). "The six unshared genes (CEBPB, BMP6, PTGS2, DMP1, FGF2, and H2AFV) are likely the important contributors to the ossifying phenotype seen in the metastatic synovial sarcomas." (PMID 32290096, 2020).
thyroid neoplasm (1 paper, 2006). "CEBPB also has been shown to be a regulator of Cox-2; Cox-2 has recently been implicated as a potential biomarker in thyroid neoplasm." (PMID 17156473, 2006).
vaginal candidiasis (1 paper, 2015). "The gene encoding CEBPβ is upregulated in human epithelial and endothelial cells in response to Candida exposure as well as in samples from women with vaginal candidiasis." (PMID 26317211, 2015).
tumor (294 papers, 1999 to 2026). "In contrast to CEBPA, an increase in CEBPB expression has been associated with worse oncological outcomes in several tumor types including prostate, breast, and colon." (PMID 40226120, 2025). "The high expression of CEBPB is associated with higher TMErisk scores, indicating its potential role in promoting tumor growth and poor prognosis." (PMID 40104502, 2025). "Further, we investigated the potential driver transcription factors (TFs) using SCENIC and found that E2F1 and CEBPB, associated with proliferation and stemness, were significantly upregulated in L‐side tumor cells, which further proved our above finding." (PMID 39716897, 2024). "In contrast, correlations between the change in malignant cells caused by CEBPB inhibition and tumor microenvironment perturbation should still be further studied." (PMID 36353635, 2022). "An animal model with an intact immune system along with CEBPB perturbation would be more precise for exploring associations between CEBPB and the tumor microenvironment." (PMID 36353635, 2022). "MiR-155 is expressed both in CRC cells and in the tumor immune infiltrates, with the presence of CEBPB pointing to tumor-associated macrophages as additional actors in drug resistance." (PMID 34503164, 2021). "Recent molecular studies have reported that aberrant tumor glycolysis regulates the CEBPB signaling axis and modulates the tumor-associated Myeloid-Derived Suppressor Cells through interconnected autophagy and pyroptosis pathways, thereby maintaining the immunosuppressive phenotype within the TME." (PMID 40145099, 2025). "We discovered that inhibiting SPP1 reversed the tumor progression and extended survival times caused by the overexpression of CEBPB in vivo, which was associated to change the number of SPP1/Integrin αvβ1/phosphorylated-Akt-positive M2 TAMs in the xenograft tumors." (PMID 38994023, 2024). "Furthermore, immunohistochemistry (IHC) demonstrated that BF-TK/GCV reduced the expression of HIF−1α, mTOR, NF-κB1-p105, VCAM1, MMP13, CXCL12, ATG16, and CEBPB, which were associated with tumor metastasis." (PMID 37511481, 2023). "Loss of CEBPB reduced ether lipids, reactivated CPT1A, and impaired Akt signaling, diminishing tumor growth and lipid content in vitro and in vivo." (PMID 41565622, 2026). "In the intercellular correlation analysis of gene expression, tumor epithelial cell CEBPB expression was significantly correlated with cytotoxic T-lymphocyte associated protein 4 (CTLA4) expression in T cells, especially in regulatory and exhausted T cells." (PMID 41743630, 2026). "CEBPB was identified as highly expressed in dormant tumor cells, where it maintained tumor dormancy by transcriptionally activating cell cycle negative regulators, particularly CCNG2." (PMID 41799200, 2026). "CCK-8, colony formation, and PI staining assay were performed to identify CEBPB as a key factor in tumor dormancy maintenance." (PMID 41799200, 2026). "In vitro co-culture experiments also showed that tumor cell CEBPB overexpression increased CTLA4 in T cells." (PMID 41743630, 2026). "Co-expression analysis highlights genes like PIK3R5 (PI3K–AKT signaling), CEBPB (linking inflammation to tumor progression), and STAT2 (JAK–STAT amplification)." (PMID 41303731, 2025). "Analysis of human and rodent tumor cells has shown that CEBPB has pro-oncogenic functions and is essential for the development of many cancers." (PMID 40226120, 2025). "Knockdown of CEBPB in HCT116 cells rescued DUSP1 expression and reduced pro-tumor pathways linked to hyperactive MAPK." (PMID 41411347, 2025). "PD analysis was limited to the group which showed statistically significant tumor reduction —TfR-(h/m)siCEBPB, highlighting the biological relevance of CEBPB mRNA expression patterns and their implications in the therapeutic efficacy." (PMID 40226120, 2025). "After treatment with TfR-siCEBPB, downregulation of CEBPB mRNA in the liver and tumor tissue of metastatic PDAC model animals was evident." (PMID 40226120, 2025).
tumor (continued). "As an oncogene, CEBPB can promote tumor growth and progression by enhancing cell proliferation, energy metabolism, invasion, and growth and specifically in differentiation of myeloid and lymphoid cell survival." (PMID 40226120, 2025). "In this work, we show evidence that a nucleic acid–based therapy, formed by the combination of a TfR targeting RNA aptamer and an siRNA for CEBPB, has potential for treatment of both primary tumor and metastatic lesions in the liver." (PMID 40226120, 2025). "PDAC is characterized by a dense stromal reaction and a highly desmoplastic environment, where CEBPB has been found to contribute to the fibrotic response and to modulate the tumor microenvironment." (PMID 40226120, 2025). "In breast cancer, CEBPB has been implicated in driving partial epithelial-to-mesenchymal transition (EMT), regulating tumor-promoting cytokines, and shaping the immunosuppressive microenvironment." (PMID 41411347, 2025). "Upregulation of miR‐155 in MASLD models reduces CCAAT enhancer binding protein beta (C/EBP‐β), contributing to tumor progression." (PMID 40693828, 2025). "Functional characterization of the CEBPB-CAF-C3 cell type demonstrated its crucial role in tumor progression and therapeutic resistance through activation of drug resistance pathways and immunomodulatory mechanisms." (PMID 40145099, 2025). "By analyzing alterations in the levels of these proteins following modifications to CEBPB expression or activity, researchers aim to elucidate how CEBPB facilitates tumor growth and metastasis." (PMID 40487290, 2025). "Future investigations will concentrate on the transformation of colon epithelial cells and tumor cells to gain a deeper understanding of how CEBPB functions in UCCRC." (PMID 40487290, 2025). "Although these results are based primarily on computational analysis and lack experimental validation, they provide valuable insights into the role of CEBPB in the tumor immune microenvironment." (PMID 40949418, 2025). "Activation of the CREB1/CEBPB axis can promote the expression of M2 macrophage markers, and the precise identification of crucial factors governing CREB1/CEBPB axis-mediated M2 macrophage regulation within the tumor microenvironment remains elusive." (PMID 38243273, 2024). "CEBPB is an important cytokines response transcription factor, the chemokines CXCL12 induced recruitment of Tregs via CEBPB/NF-κB signaling to promote drug resistance, thus the inhibition of CEBPB benefited the tumor treatment." (PMID 38227591, 2024). "Based on the TCGA-CRC dataset, CEBPB expression was significantly higher compared to adjacent non-tumor tissue (P < 0.001), and KM curves showed that OS and disease-specific survival were shorter in the high CEBPB expression group (P = 0.010)." (PMID 38710698, 2024). "As a specific transcriptional regulon within GBM subcluster 6, CEBPB plays a crucial role in determining the tumor characteristics of this subgroup." (PMID 38994023, 2024). "Scenic analysis also revealed markedly rich transcriptional activity in high APJ ECs compared to low APJ ECs, including TFs associated with tumour progression and pro‐angiogenic pathways such as NFKb, JUNK‐STAT, CEBPB." (PMID 39434201, 2024). "In HB non-tumor and tumor regions, similar level of expression of CEBPB and FGFR2 were localized at the liver parenchyma." (PMID 36996081, 2023). "Nevertheless, novel reports show that MEN1 interacts with histone deacetylases to repress CCAAT enhancer binding protein beta (C/EBPB) expression during TGF-beta signaling, inducing EMT and preventing C/EBPB-mediated tumor suppression." (PMID 37659057, 2023). "Percentages of CEBPB-immuno-positive bile duct cells were comparable between CC and HB tumor region, but both were significantly higher than that of HB non-tumor livers." (PMID 36996081, 2023). "Percentages of bile duct cells that were CEBPB+ve were comparable between CC and HB tumor region, but were significantly higher than that of HB non-tumor livers." (PMID 36996081, 2023).
tumor (continued). "Here, invasion of a collagen-rich matrix was induced by tumor cells via the IL-1β/CEBPβ/MMP pathway." (PMID 36423636, 2022). "To explore if CEBPB was specifically expressed in some cell types in the TME of metastatic SKCM tumor tissue, we analyzed its mRNA level in a single cell RNA-seq dataset (GSE115978) of metastatic SKCM patients across multiple cell types." (PMID 36353635, 2022). "The results showed that high CEBPB expression is associated with a favorable prognosis of metastatic SKCM and activated immune response-related pathways in bulk tumor tissue as well as pure macrophages." (PMID 36353635, 2022). "High CEBPB expression is significantly associated with active inflammation and immune response pathways in both macrophages and bulk SKCM tumor tissues." (PMID 36353635, 2022). "Concordantly, CEBPB eRNA levels are significantly elevated in HCC tumours compared with non-tumour tissues." (PMID 36039999, 2022). "CEBPB eRNAs exhibit pro-tumorigenic properties via methylation-regulated control of CEBPB transcription, and their depletion significantly reduces tumour cell growth and invasiveness." (PMID 36039999, 2022). "ASS1, regulated by ATF4 and CEBPβ in tumor cells, is increased to enhance the synthesis of arginine from citrulline." (PMID 36231064, 2022). "miR-155 was previously shown to regulate inflammatory cytokine production (IL-6, IL-10 and TNFα) in tumor-activated macrophages via targeting CEBPB." (PMID 33540559, 2021). "Mechanistically, tumor-secreted factors and GM-CSF + IL-6 signaling activates Stat3 and Cebpβ leading to the expression of miR-21a, miR-21b, and miR-181b." (PMID 33133086, 2020). "Immunostaining of ID8 omental tumours revealed significant increase in frequency of nuclear p65RelA, cJun and cEBPβ in both tumour cells and the juxtra-tumoral adipocytes in SP–/– tumours compared with the SP+/+ tumours." (PMID 30765860, 2019). "Nevertheless, the correlation between FOXO1/CEBPB/NF-κB and drug resistance-induced tumor progression is reported in some studies." (PMID 31395078, 2019). "The transcription factor (TF) CCAAT/enhancer binding protein beta (CEBPB) is important for maintaining the tumor initiating capacity and invasion ability." (PMID 27716259, 2016). "In summary, our results implicate the IL-1β/CEBPβ/MMP signaling pathway as a major mediator of RCC tumor cell invasion, and this pathway should be considered in the design of preclinical models of RCC to test its target-ability as an anti-metastatic therapy." (PMID 23342250, 2012). "We conclude from this study that the IL-1β/CEBPβ/MMP pathway is a major mediator of RCC tumor invasion and should be considered in the design of molecularly targeted therapeutics." (PMID 23342250, 2012). "Using RNA interference, we next demonstrated that IL-1β-induced RCC tumor cell invasion required CEBPβ." (PMID 23342250, 2012). "Notably, high CEBPB expression orchestrated a tumor-supportive microenvironment with macrophage recruitment, M2 macrophage polarization, and T cell suppression." (PMID 41799200, 2026). "However, studies over the past decade have revealed multifaceted roles for CEBPB in various cancers, where it can either promote or suppress tumor growth, depending on the cellular context and interacting cofactors." (PMID 41411347, 2025). "Additionally, EP300, a histone acetyltransferase, was found to interact with CEBPB, suggesting a cooperative mechanism that amplifies CEBPB-driven transcriptional activation of tumor-promoting and immune-related genes." (PMID 40949418, 2025). "The CEBPB gene in the model played crucial roles in tumor progression." (PMID 40550050, 2025). "Importantly, CEBPB mRNA knockdown was evident in liver tissue, with average transcript downregulation of ~45%, along with an apparent ~25% knockdown in tumor tissue, relative to the saline control group." (PMID 40226120, 2025).